ZNF469 (zinc finger protein 469)
Description:
May be involved in transcriptional regulation.
Synonyms: KIAA1858; Zfp469; BCS; BCS1
Tractability: PROTAC: ubiquitination databases record sites on it.
Gene: Protein-coding gene on chromosome 16 (88,382,959 to 88,440,757, forward strand). Ensembl gene ENSG00000225614.
Subcellular location: Nucleus
Subcellular location (Human Protein Atlas): Nucleoplasm; Cell Junctions
Gene Ontology:
Molecular function: DNA-binding transcription factor activity
Biological process: negative regulation of transcription by RNA polymerase II; regulation of extracellular matrix organization
Cellular component: nucleus
Genetic constraint (gnomAD): Loss-of-function variants: 1 observed, 2.15 expected, observed/expected ratio (o/e) 0.47, 90% interval 0.16 to 1.71. That is too few expected variants to judge how well the gene tolerates losing a copy. Missense variants: 6,099 observed, 5,301 expected, observed/expected ratio (o/e) 1.15, 90% interval 1.13 to 1.17. Synonymous variants: 2,703 observed, 2,352.5 expected, observed/expected ratio (o/e) 1.15, 90% interval 1.11 to 1.19.
Homologues: Orthologues: macaque ZNF469 (88% identical), dog ZNF469 (52% identical), mouse Zfp469 (46% identical), rat Zfp469 (46% identical), tropical clawed frog znf469 (21% identical).